SCGB3A1 (secretoglobin family 3A member 1)
Description:
Secreted cytokine-like protein. Inhibits cell growth in vitro.
Synonyms: PnSP-2; HIN1; UGRP2; HIN-1; LU105
Tractability: Antibody: UniProt places it where antibodies can reach, with high confidence; UniProt predicts a signal peptide or a membrane-spanning region; its Gene Ontology location is reachable by antibodies, with medium confidence.
Gene: Protein-coding gene on chromosome 5 (180,590,105 to 180,591,499, reverse strand). Ensembl gene ENSG00000161055.
Subcellular location: Secreted
Gene Ontology:
Molecular function: protein binding; cytokine activity
Biological process: negative regulation of cell growth; positive regulation of myoblast fusion; regulation of cell population proliferation; signal transduction
Cellular component: extracellular exosome; extracellular region
Genetic constraint (gnomAD): Loss-of-function variants: 7 observed, 5.43 expected, observed/expected ratio (o/e) 1.29, 90% interval 0.71 to 1.89. That is too few expected variants to judge how well the gene tolerates losing a copy. Missense variants: 119 observed, 109.21 expected, observed/expected ratio (o/e) 1.09, 90% interval 0.94 to 1.27. Synonymous variants: 67 observed, 55.7 expected, observed/expected ratio (o/e) 1.2, 90% interval 0.99 to 1.47.
Homologues: Orthologues: chimpanzee SCGB3A1 (95% identical), macaque SCGB3A1 (81% identical), rabbit SCGB3A1 (61% identical), guinea pig SCGB3A1 (59% identical), mouse Scgb3a1 (58% identical), pig SCGB3A1 (58% identical), rat Scgb3a1 (53% identical). Paralogues in human: SCGB3A2 (42% identical).
Diseases named in the same sentence as SCGB3A1 in open-access papers:
SCGB3A1 is named in the same sentence as 37 diseases in open-access papers, as found by Europe PMC text mining. Sharing a sentence is not in itself a finding about the gene and the disease. The quoted sentences say what the papers report.
breast carcinoma (12 papers, 2011 to 2025). "Importantly, Kaplan–Meier analysis showed that activin B and SCGB3A1 signatures were both associated with poor clinical outcome in patients with breast cancer." (PMID 35469015, 2022). "Kaplan–Meier survival analysis indicated that patients with breast cancer with elevated SCGB3A1 levels had significantly shorter survival times." (PMID 40357856, 2025). "To explore this connection further, we performed transcriptomic analysis on SUM159 breast cancer cells treated with activin B or SCGB3A1 and revealed their respective response signatures." (PMID 35469015, 2022). "The results suggest a putative role for INHBB and SCGB3A1 in the promotion of stem cell properties in breast cancer cells." (PMID 35469015, 2022). "Specific ligand‐receptor interactions were observed between these epithelial subtypes and fibroblasts, with significant interactions between CD74‐APP receptors in SCGB3A1‐Epi and Fib‐11 in breast cancer and between SPP1‐CD44 receptors in KLK10‐Epi and Fib‐11 in PDAC." (PMID 40357856, 2025). "To investigate the potential stem cell phenotype associated with activin B or SCGB3A1 signatures in clinical samples, we stratified gene expression datasets from breast cancer patients (METABRIC or lung metastasis samples) based on expression of activin B or SCGB3A1 signatures." (PMID 35469015, 2022). "Women with methylation of the SCGB3A1-promoter may be at risk of developing luminal, but not basal-like, breast cancer and a reduction in serum estradiol levels may be protective for these women." (PMID 21812955, 2011). "Considering these results, we stimulated SUM159-LM1 breast cancer cells with either recombinant activin B, a homodimer of INHBB, or recombinant SCGB3A1, and this also induced sphere formation by cancer cells." (PMID 35469015, 2022). "Five of these genes were found to be significantly methylated in breast cancers from our cohort in Senegal (APC, RASSF1, GASTP1, SCGB3a1, and HS3ST2)." (PMID 31819783, 2019). "Interestingly, our results show that SCGB3A1‐Epi and KLK10‐Epi are key drivers of liver metastasis in breast cancer and PDAC, respectively." (PMID 40357856, 2025). "Though there is no study yet to investigate the relationship between SCGB3A1 and prostate cancer, it has been found to be upregulated in breast cancer and testicular cancer." (PMID 36500247, 2022). "The sphere-forming ability of breast cancer cells was markedly increased when treated with CM containing INHBB or SCGB3A1, but not with OPG or LAMA1." (PMID 35469015, 2022). "The same study reported demethylation of retinoic acid receptor β (RARB2) and secretoglobin family 3A member 1 (SCGB3A1) in noncancerous breast cancer cells following lycopene treatment." (PMID 32917280, 2020). "DNA promoter methylation of a gene panel including APC, CCND2, RARB, RASSF1A, and SCGB3A1 in breast cancer samples was not correlated with age in a previous study." (PMID 27028854, 2016).
lung carcinoma (6 papers, 2010 to 2024). "Consistent with its putative tumor-suppressor function, SCGB3A1, is aberrantly methylated in various types of cancer, including lung carcinomas." (PMID 22375630, 2012). "Genes frequently methylated in lung cancer cell lines including SCGB3A1, ID4, CCND2 were found among the most commonly methylated in the lung tumors analyzed." (PMID 20849603, 2010). "“PanCancer” panel (APC, FOXA1, RASSF1A) detected cancer with 72.4% sensitivity, 73.5% specificity and 72.8% accuracy.“CancerType” panel (SCGB3A1, SEPT9, and SOX17) discriminated TOO with 80.0%, 98.9%, and 85.1% specificity for breast, colorectal, and lung cancer, respectively." (PMID 36980276, 2023). "The data indicated that the CCNE1-high, CCNE1-high/EGR1-low, CCNE1-high/SCGB3A1-low and OTX1-high/CCNE1-high phenotypes, which might be involved in lung cancer malignancy, are related to poor prognosis in lung cancer." (PMID 36918558, 2023). "However, seven genes selected from FSL (FOXA2, C4BPA, SCGB3A1, DDX58, CCNDBP, TMSB4X, and CXCL17), and one gene selected from both FSL as well as RSL (CD9), were up-regulated in the lung cancer tissues, but not significantly (P > 0.05)." (PMID 23374247, 2013).
prostate carcinoma (4 papers, 2009 to 2022). A carcinoma that arises from epithelial cells of the prostate gland. "RARB and SCGB3A1 proved to be independent variables that indicated a relative risk of there being prostate cancer of 1.14 (95 % CI 0.99–1.31, P = 0.058) and 1.10 (95 % CI 1.01–1.21, P = 0.028), respectively." (PMID 27576364, 2016). "SCGB3A1, a marker for club cells, was one of the top downregulated genes in prostate cancer club cells compared to club cells from normal healthy control prostates." (PMID 35013146, 2022). "In comparison to the discovery cohort, the identified EV proteins (i.e., SERPINA3, LRG1, and SCGB3A1) gained from the validation cohort clearly complied with the discovery cohort, which indicated the effect of the identified EV proteins on prostate cancer were stable." (PMID 36500247, 2022). "Prostate club cells in the normal epithelia may play a tumor suppressor role through secretion of SCGB3A1 which is then downregulated in concert with prostate cancer progression, as marked by our finding of SCGB3A1low club cells in prostate cancer tissues that can be propagated in organoids." (PMID 35013146, 2022). "We observed several EV proteins, particularly SERPINA3, LRG1, and SCGB3A1, which showed a consistent difference between prostate cancer cases and non-prostate cancer controls across three DIA methods, which could be suggested as potential biomarkers and deserve further verification." (PMID 36500247, 2022). "The clustering yielded a clear pattern of the five upregulated EV proteins (i.e., SERPINA3, SCGB3A1, LRG1, SERPINA6, and CP) enriched in the prostate cancer cases." (PMID 36500247, 2022). "Our preliminary results, obtained in a single-institution study with limited enrolment, showed that the hypermethylation of GSTP1, RARB, RASSF1, SCGB3A1 and CCND2 was highly tumour-specific in prostate cancer tissue." (PMID 27576364, 2016). "We identified five highly methylated genes in prostate cancer: GSTP1, RARB, RASSF1, SCGB3A1, CCND2 (P < 0.0001), with an area under the ROC curve varying between 0.89 (95 % CI 0.82–0.97) and 0.95 (95 % CI 0.90–1.00)." (PMID 27576364, 2016). "Our preliminary results highlighted that hypermethylation of GSTP1, RARB, RASSF1, SCGB3A1 and CCND2 was highly tumour-specific in prostate cancer tissue." (PMID 27576364, 2016). "Although SCGB3A1 and CCND2 methylation in prostate cancer has been reported, the possibility of using these markers for the early diagnosis of PCa has never been fully investigated." (PMID 27576364, 2016). "We assessed the levels of urinary EV-associated proteins based on 40 samples consisting of 20 cases and 20 controls, where 18 EV proteins were identified to be differentiated in prostate cancer outcome, of which three (i.e., SERPINA3, LRG1, and SCGB3A1) were shown to be consistently upregulated." (PMID 36500247, 2022).
pancreatic carcinomas (3 papers, 2008 to 2022). "Methylation patterns of the human SCGB3A1 gene promoter have been extensively studied and a correlation of methylation and loss of SCGB3A1 expression and malignant phenotypes is well established in many human cancers including breast, prostate, lung, and pancreatic carcinomas." (PMID 18194566, 2008). "Silencing of SCGB3A1 expression through methylation is well-established in human breast, lung, prostate, and pancreatic cancers." (PMID 34069906, 2021). "Moreover, SCGB3A1 has been reported as a tumour suppressor in various human tumours including breast, prostate, lung and pancreatic carcinomas." (PMID 34877770, 2022).
asthma (2 papers, 2018 to 2025). "We identified 8 key genes (LOC100132287, CEACAM5, PRR4, CPA3, POSTN, LYPD2, TCN1, and SCGB3A1) associated with asthma by combining the LASSO regression model and the SVM-RFE method." (PMID 39963184, 2025). "LOC100132287, LYPD2, SCGB3A1 and C7orf26 (Chromosome 7 open reading frame 26) had low expression in asthma patients." (PMID 39963184, 2025). "The association of the five genes CEACAM5, POSTN, TCN1, SCGB3A1, and CPA3 with asthma has been extensively identified and validated, and these are the most highly upregulated genes in patients with asthma, and CEACAM5 is associated with resting mast cells and eosinophils." (PMID 39963184, 2025). "The gene SCGB3A1 is highly expressed in sputum columnar cells in patients with severe asthma and associated with non-neutrophilic airway inflammation." (PMID 39963184, 2025).
seminoma (2 papers, 2020 to 2022). A radiosensitive malignant germ cell tumor found in the testis (especially undescended), and extragonadal sites (anterior mediastinum and pineal gland). "Seminomas are known to show selective hypermethylation at several tumor suppressors, such as MGMT, SCGB3A1, RASSF1A, HIC1, and PRSS21." (PMID 32176716, 2020).
adenoma (1 paper, 2008). A neoplasm arising from the epithelium. "ADAMTS1, CDKN2A, CRABP1, MLH1, NR3C1, RUNX3, and SCGB3A1 showed increasing methylation frequencies from adenomas to carcinomas, while HOXA9, MAL, and MGMT displayed overall equal methylation frequencies in all tumor subgroups." (PMID 19117505, 2008).
colon adenocarcinoma (1 paper, 2021). "A cluster of 13 CpG loci (11 genes) were identified that displayed differential methylation in colon adenocarcinoma (COAD) (N = 289) compared to normal colon tissues (N = 38): ZNF671, TWIST1 (two CpG loci), TMEFF2, TM6SF1, GAS7, MAL, HIN1 (two CpG loci; SCGB3A1), COL6A2, AKR1B1, GPX7, ARHGEF7)." (PMID 34903270, 2021).
Duchenne muscular dystrophy (1 paper, 2025). Duchenne muscular dystrophy (DMD) is a neuromuscular disease characterized by rapidly progressive muscle weakness and wasting due to degeneration of skeletal, smooth and cardiac muscle. "On the other hand, embryonic MyHC (MyHC-emb), which is known to be re-expressed during early muscle regeneration and in many muscle diseases such as Duchenne muscular dystrophy, was more broadly detected in Scgb3a1−/− TA muscles than in Scgb3a1+/+ muscles (white arrow)." (PMID 41469838, 2025).
idiopathic pulmonary fibrosis (1 paper, 2022). Idiopathic pulmonary fibrosis (IPF) is a nonneoplastic pulmonary disease that is characterized by the formation of scar tissue within the lungs in the absence of any known cause. "Scgb3a1 is expressed in secretory cells in idiopathic pulmonary fibrosis." (PMID 35714115, 2022).
Lyme disease (1 paper, 2024). Lyme disease (named after the towns in the USA where the disease was first identified) is a bacterial infection caused by Borrelia burgdorferi. "To investigate the impact of SCGB1D2 on Bb establishing infection in vivo, we injected C57BL/6 J female mice aged at 10 weeks at the time of infection intradermally with Bb incubated with either SCGB1D2 or SCGB3A1, a secretoglobin that does not associate with Lyme disease." (PMID 38503741, 2024).
metastatic disease (1 paper, 2010). "When comparing methylation rates in localized tumors versus metastatic disease, the methylation of RUNX3 (p = 0.013), SCGB3A1-2 (p = 0.008), SFRP4-2 (p = 0.022), and DLC1 (p = 0.016) was significantly associated with the presence of metastatic disease." (PMID 20849603, 2010). "Methylation of RUNX3, SCGB3A1, SFRP4, and DLC1 was significantly associated with the extent of the disease when comparing localized versus metastatic tumors." (PMID 20849603, 2010).
nasopharyngeal carcinoma (1 paper, 2016). A carcinoma arising from the nasopharyngeal epithelium. "SCGB3A1 is a growth-inhibitory cytokine which is downregulated in the majority of prostate, breast, lung, pancreatic and nasopharyngeal cancers due to DNA promoter hypermethylation." (PMID 27576364, 2016).
ovarian carcinoma (1 paper, 2007). A malignant neoplasm originating from the surface ovarian epithelium. "APC, CDH13, CRABP1, HOXA9, HOXB5, RASSF1A, and SCGB3A1 were found to be hypermethylated both in the primary tumours and in ovarian cancer cell lines, whereas ADAMTS1 and MGMT were hypermethylated only among cell lines." (PMID 17623056, 2007). "CDH13, CRABP1, HOXA9, and SCGB3A1 were subjected to direct bisulphite sequencing in the four ovarian carcinoma cell lines." (PMID 17623056, 2007). "We demonstrate here that SCGB3A1 promoter hypermethylation also occurs in ovarian carcinomas, suggesting that this event plays a role in the development of a subgroup of these tumours." (PMID 17623056, 2007). "CpG island promoter hypermethylation of tumour suppressor genes is a common event in primary ovarian carcinomas and cell lines, and HOXA9, HOXB5, SCGB3A1, and CRABP1, represent novel hypermethylated target genes in this disease." (PMID 17623056, 2007). "The investigated gene promoters were chosen from loci previously reported to be methylated in ovarian cancer (n = 7; APC, CDH13, MGMT, MLH1, p14ARF, p16INK4a, RASSF1A) and from loci methylated in other tumour types (n = 6; ADAMTS1, CRABP1, HOXA9, HOXB5, NR3C1, SCGB3A1)." (PMID 17623056, 2007).
ovarian clear cell adenocarcinoma (1 paper, 2021). A malignant glandular epithelial neoplasm characterized by the presence of clear and hobnail cells. "Methylation of its promoter had been reported to be associated with poor outcome in patients with ovarian clear cell adenocarcinoma, and expression of the SCGB3A1 gene can increase paclitaxel sensitivity via the Akt pathway." (PMID 34566519, 2021).
ovarian tumours (1 paper, 2007). "Even though APC and SCGB3A1 promoter methylation is less frequent, it is nevertheless associated with early stage ovarian tumours and might also have a diagnostic potential." (PMID 17623056, 2007).
prostate tumour (1 paper, 2016). "There are few studies in literature on the hypermethylation of SCGB3A1 and CCND2 in prostate tumour tissue." (PMID 27576364, 2016).
pterygium (1 paper, 2021). A wedge-shaped fibrovascular lesion arising from the bulbar conjunctiva and extending to the cornea. "Among the top DEGs were four genes encoding tumor suppressors that were downregulated in pterygium: C10orf90, RARRES1, DMBT1 and SCGB3A1; C10orf90 and RARRES1 were also downregulated in pinguecula." (PMID 34769520, 2021). "RARRES1 and SCGB3A1 were identified in previous pterygium gene profiling studies, while C10orf90 and DMBT1 are new." (PMID 34769520, 2021). "Moreover, the previous RNA-seq study reported SCGB3A1 as one of the top downregulated DEGs in pterygium." (PMID 34769520, 2021).
rhabdomyosarcoma (1 paper, 2025). A rare aggressive malignant mesenchymal neoplasm arising from skeletal muscle. "Furthermore, high percentage of aberrant methylation of SCGB3A1 promoter in rhabdomyosarcoma patients indicates SCGB3A1 should be considered as a potential clinical target for assessment of the most common type of soft tissue sarcoma for children." (PMID 41469838, 2025).
tumor (23 papers, 2007 to 2025). "Evidently, the SCGB3A1 tumor suppressive functions were illustrated as the inhibition of malignant cell growth, invasion, and migration through the AKT signaling pathway." (PMID 34069906, 2021). "The methylation of the same genes was also associated with tumor stage RUNX3 (p = 0.040), SCGB3A1 (p = 0.032), SFRP4 (p = 0.033), and DLC1 (p = 0.035)." (PMID 20849603, 2010). "The AKT signaling pathway is responsible for the SCGB3A1's tumor suppressor function as characterized by inhibition of cell growth, cell migration and invasion." (PMID 18194566, 2008). "In the tumour activation samples, SCGB3A1 and SCGB3A2, were highly expressed." (PMID 39187937, 2024). "Based on previous observations, the quantitative data in the present study suggests that SCGB3A1 could be a major steady-state tumor-suppressor gene in the human SAE." (PMID 22375630, 2012). "Specific expression of SCGB3A1 in lung airway epithelial cells may imply an important function for SCGB3A1 in the maintenance of lung homeostasis such as clearance of pathogens, in addition to tumor suppressor function, however, its role in other tissues, if any, has not been explored." (PMID 41469838, 2025). "Furthermore, SCGB3A1 was originally identified in both mouse and human tumor specimens." (PMID 34069906, 2021). "Most interesting were the 4 genes that function as tumor suppressors: C10orf90, RARRES1, DMBT1, and SCGB3A1." (PMID 34769520, 2021). "We also highlighted a similar methylation profile for healthy prostatic tissue adjacent to the tumour and healthy non prostatic tissue, with the exception of CASP8 and SCGB3A1, which showed a statistically higher methylation in the former." (PMID 27576364, 2016). "DNA hypermethylation of tumour suppressor genes seems to play an important role in ovarian carcinogenesis and HOXA9, HOXB5, SCGB3A1, and CRABP1 are identified as novel hypermethylated target genes in this tumour type." (PMID 17623056, 2007). "Our qRT‐PCR results revealed that the expression levels of TNFSF10 (p < 0.01), ECM1 (p < 0.01), and RNF213 (p < 0.01) were significantly increased in advanced LUAD tumor cells, whereas the expression of SCGB3A2 (p < 0.01), SCGB3A1 (p < 0.01), and SFTPC (p < 0.01) was increased in early LUAD." (PMID 33783985, 2021). "With the exception of HOXB5, higher promoter methylation frequencies were found among tumours from patients with relatively early FIGO stages (I-II) than late stages, but reached statistical significance only for HOXA9 and SCGB3A1 (P = 0.002, P = 0.020, respectively)." (PMID 17623056, 2007).